FAM90A8 (family with sequence similarity 90 member A8)
Synonyms: FAM90A8P
Tractability: No criterion of Open Targets' tractability assessment is met for any kind of drug.
Gene: Protein-coding gene on chromosome 8 (7,738,387 to 7,741,396, forward strand). Ensembl gene ENSG00000285937.
Subcellular location (Human Protein Atlas): Nucleoplasm; Nucleoli
Homologues: Orthologues: mouse Fam90a1b (28% identical), mouse Fam90a1a (27% identical), rat Fam90a1l1 (26% identical). Paralogues in human: FAM90A16 (99% identical), FAM90A17 (99% identical), FAM90A9 (99% identical), FAM90A18 (98% identical), FAM90A19 (98% identical), FAM90A13 (98% identical), FAM90A10 (98% identical), FAM90A15 (98% identical), FAM90A23 (98% identical), FAM90A24 (98% identical), FAM90A14 (97% identical), FAM90A3 (97% identical), and 9 more.